SIMC1 (SUMO interacting motifs containing 1)
Description:
Plays a role in SMC5-SMC6 complex recruitment for viral restriction. Forms a complex with SLF2 and this complex is required to recruit SMC5-SMC6 complex to PML nuclear bodies and sites of viral replication. [Isoform 1]: Inhibits the protease activity of CAPN3. [Isoform 5]: Inhibits the protease activity of CAPN3.
Synonyms: C5orf25; PLEIAD; FLJ44216; OOMA1
Tractability: PROTAC: ubiquitination databases record sites on it; its protein half-life has been measured.
Gene: Protein-coding gene on chromosome 5 (176,238,367 to 176,345,991, forward strand). Ensembl gene ENSG00000170085.
Subcellular location: Nucleus, PML body; Cytoplasm (Isoform 5); Cytoplasm, myofibril, sarcomere
Subcellular location (Human Protein Atlas): Nucleoplasm; Nucleoli fibrillar center
Gene Ontology:
Molecular function: peptidase inhibitor activity; protein binding; SUMO polymer binding
Cellular component: cytoplasm; nucleoplasm; PML body; sarcomere
Genetic constraint (gnomAD): Loss-of-function variants: 58 observed, 81.3 expected, observed/expected ratio (o/e) 0.71, 90% interval 0.58 to 0.89. The upper end of that interval is the gene's LOEUF score, 0.89, which puts it in group 3 of 6, group 1 being the genes least tolerant of losing a copy. Missense variants: 913 observed, 1,059.1 expected, observed/expected ratio (o/e) 0.86, 90% interval 0.82 to 0.91. Synonymous variants: 353 observed, 397.53 expected, observed/expected ratio (o/e) 0.89, 90% interval 0.81 to 0.97.
Homologues: Orthologues: chimpanzee SIMC1 (99% identical), macaque SIMC1 (95% identical), dog SIMC1 (86% identical), mouse Simc1 (80% identical), rabbit SIMC1 (80% identical), rat Simc1 (80% identical), tropical clawed frog simc1 (25% identical), zebrafish simc1 (20% identical). Paralogues in human: SKIDA1 (7% identical), EPOP (5% identical).
Diseases named in the same sentence as SIMC1 in open-access papers:
SIMC1 is named in the same sentence as 2 diseases in open-access papers, as found by Europe PMC text mining. Sharing a sentence is not in itself a finding about the gene and the disease. The quoted sentences say what the papers report.
cancer (1 paper, 2026). A tumor composed of atypical neoplastic, often pleomorphic cells that invade other tissues. "In mammals, the Sbno2 gene is associated with cancer cell proliferation and survival, while the Simc1 gene encoded protein, SIMC1, interacts with the CTBP1 protein, which is involved in the ability of cancer cells to evade cell-cycle checkpoints." (PMID 41481677, 2026).
SIMC1 also shares sentences with these, for which no sentence is quoted: viral infections (1 paper).